REC114 (REC114 meiotic recombination protein)
Description:
Required for DNA double-strand breaks (DSBs) formation in unsynapsed regions during meiotic recombination. Activates DSBs formation in unsynapsed regions, an essential step to ensure completion of synapsis (By similarity). Required for both spermatogenesis and oogenesis.
Synonyms: C15orf60; LOC283677; FLJ27520; FLJ36860; FLJ44083; CT147; OOMD10; OZEMA10
Tractability: No criterion of Open Targets' tractability assessment is met for any kind of drug.
Gene: Protein-coding gene on chromosome 15 (73,443,164 to 73,560,013, forward strand). Ensembl gene ENSG00000183324.
Subcellular location: Chromosome
Gene Ontology:
Molecular function: protein binding
Biological process: meiotic DNA double-strand break formation; oogenesis; spermatogenesis
Cellular component: chromosome; condensed nuclear chromosome
Genetic constraint (gnomAD): Loss-of-function variants: 25 observed, 27.55 expected, observed/expected ratio (o/e) 0.91, 90% interval 0.66 to 1.27. The upper end of that interval is the gene's LOEUF score, 1.27, which puts it in group 5 of 6, group 1 being the genes least tolerant of losing a copy. Missense variants: 315 observed, 286.52 expected, observed/expected ratio (o/e) 1.1, 90% interval 1 to 1.21. Synonymous variants: 124 observed, 113.5 expected, observed/expected ratio (o/e) 1.09, 90% interval 0.94 to 1.27.
Homologues: Orthologues: chimpanzee REC114 (99% identical), macaque REC114 (95% identical), pig REC114 (76% identical), mouse Rec114 (67% identical), dog REC114 (63% identical), rabbit REC114 (61% identical), rat Rec114 (54% identical), tropical clawed frog REC114 (29% identical), zebrafish rec114 (23% identical).
Diseases named in the same sentence as REC114 in open-access papers:
REC114 is named in the same sentence as 6 diseases in open-access papers, as found by Europe PMC text mining. Sharing a sentence is not in itself a finding about the gene and the disease. The quoted sentences say what the papers report.
Infertility (3 papers, 2024 to 2025). "Lack of Rec114 leads to NOA and POI in mice, due to defective DSB formation and aberrant homologous synapsis; in women, REC114 gene deletion leads to infertility due to supernumerary pronuclei formation at fertilization and early embryonic arrest." (PMID 38764035, 2024). "Alternatively, genes with no reported COI are enriched in gene sets associated with germ cell development and implicated in infertility mainly caused by spermatogenic failure (e.g., CATIP, CFAP65, CEP19) and oocyte/zygote/embryo maturation arrest (e.g., PADI6, REC114, WEE2)." (PMID 39202055, 2024). "Rec114-knockout mice exhibit significant defects in DSB formation, resulting in early prophase meiotic arrest and infertility." (PMID 41168699, 2025).
male infertility (3 papers, 2020 to 2025). The inability of the male to effect fertilization of an ovum after a specified period of unprotected intercourse. "Our findings expand the mutational spectrum of REC114 associated with male infertility and reinforce the genetic basis of this condition, which is crucial for improving the genetic diagnosis of NOA." (PMID 41168699, 2025). "REC114 has been recently associated with male infertility and recurrent pregnancy loss, and KO mice show affected spermatogenesis." (PMID 39678461, 2024). "We have also identified putatively causal variants in seven genes validated as aetiological factors of male infertility, such as SPAG17, REC114, TERB1, DNAH6, ADGRG2, MAMLD1, and USP26." (PMID 39678461, 2024).
hydatidiform mole (2 papers, 2021 to 2025). A gestational trophoblastic disorder characterized by marked enlargement of the chorionic villi, hyperplasia of the villous trophoblastic cells and hydropic changes. "Recent studies have found biallelic variants of MEI1 and SPO11 in males with familial nonobstructive azoospermia, and variants of TOROVIBL, MEI1, and REC114 in females with recurrent miscarriage and hydatidiform moles." (PMID 34257419, 2021).
atrial fibrillation (1 paper, 2021). A disorder characterized by an electrocardiographic finding of a supraventricular arrhythmia characterized by the replacement of consistent P waves by rapid oscillations or fibrillatory waves that vary in size, shape and timing and are accompanied by an irregular ventricular response. "Atria-Enriched GJA5, KCNA5 and NPPA, RA-Enriched HCM4, MIR100HG, REC114 and SMAD7 and Ventricles-Enriched KCNJ2, MYH7, PHLDB2, RPL2L and SLC35F1 were associated with atrial fibrillation." (PMID 34088950, 2021).
REC114 also shares sentences with these, for which no sentence is quoted: female infertility (2 papers); cancer (1).